DICER1 (dicer 1, ribonuclease III)
Diseases named in the same sentence as DICER1 in open-access papers (continued):
Sharing a sentence is not in itself a finding about the gene and the disease.
sarcoma (continued). "Primary intracranial DICER1-mutant sarcoma is a rare brain tumour, predominantly occurring in the pediatric population." (PMID 41522384, 2025). "On the other hand, new histomolecular entities have been added, like the intracranial mesenchymal tumor, FET::CREB fusion–positive, CIC-rearranged sarcoma, and primary intracranial sarcoma, DICER1-mutant." (PMID 36737790, 2023). "Unsupervised hierarchical clustering of array-based whole-genome methylation data of a subset of DICER1-mutant sarcomas has revealed that they cluster together." (PMID 36983010, 2023). "New tumor types have been added, such as the “intracranial mesenchymal tumor, FET-CREB fusion-positive”, the “CIC-rearranged sarcoma”, and the “Primary intracranial sarcoma, DICER1-mutant”." (PMID 36737790, 2023). "The methylome profile of the DICER1 mutant sarcoma was then compared with that of a high-grade glioma, a morphologically similar tumor type." (PMID 36831778, 2023). "Even if ERMS is one of the more common sarcomas in childhood, approximately a third of DICER1-related ERMS arises in patients older than 20 years." (PMID 33552988, 2020). "However, DICER1-related sarcomas, in the genitourinary tract (mostly uterine corpus and cervix) and elsewhere (including PPB), have been shown to carry strong morphological and molecular overlap regardless of their site of origin." (PMID 39847050, 2025). "Primary Intracranial DICER1-Mutant Sarcomas (PIDMS) represent a rare subset, accounting for less than 1% of all central nervous system (CNS) tumors and are thought to originate from multipotent mesenchymal progenitor cells within the leptomeninges or dural layers." (PMID 41522384, 2025). "Our main differential morphological diagnoses included CIC‐rearranged sarcoma, primary intracranial sarcoma (DICER1‐mutant), diffuse midline glioma, diffuse pediatric‐type high‐grade glioma, sarcomas, and plasmacytic‐rich meningioma, as the sarcomatoid morphology suggested a glial origin." (PMID 41473422, 2025). "Also, they are consistent with previous studies in PCCL3 rat thyroid cells and in murine sarcoma cell lines showing decreased proliferation and higher levels of apoptosis following Dicer1 silencing." (PMID 39409030, 2024). "Further methylation studies are warranted to determine whether DICER1-mutant sarcomas constitute a distinct, identifiable subclass of sarcomas." (PMID 36983010, 2023). "While the brain tumor classifier did not match a certain methylome pattern, the sarcoma classifier revealed a methylation profile compatible with a malignant Rhabdomyosarcoma-like (RMS-like) tumor with DICER1 mutation (calibrated score: 0.99)." (PMID 36380356, 2022).
sarcoma (continued). "This might—at least—in part be explained by the fact that the cohort of Peruvian patients contributed to a high proportion of non-germline-associated DICER1 mutant sarcomas, which are predominantly in the RNase IIIb domain." (PMID 40361440, 2025). "However, in the light of recent data, this type of ovarian neoplasm would probably be classified as undifferentiated SLCTS, or as the emerging entity called “DICER1-associated sarcoma” rather than fibrosarcoma." (PMID 38136408, 2023). "Primary DICER1-associated neoplasms affecting the central nervous system and eye include the following tumor types: ciliary body medulloepithelioma (CBME), pituitary blastoma, pineoblastoma, primary DICER1-associated sarcoma and embryonal tumor with multilayered rosettes." (PMID 34599283, 2022). "Sarcomas are amongst the most common neoplasms in this syndrome and DICER1-associated sarcomas exhibit several characteristic morphological features, which can aid the pathologist in suspecting an association with DICER1 PVs, irrespective of the site of origin." (PMID 36966138, 2023). "It remains unclear if the sub-clustering in DICER1-associated sarcomas into classes of SARC DICER1 and PIS DICER1 is due to a different cell of origin for CNS and non-CNS tumors, or if site-specific factors shaping the tumor microenvironment have influenced the molecular features." (PMID 36966138, 2023). "However, DICER1 variant is not specific to SLCT since it has also been described in other gynecological tract tumors, such as Sertoli cell tumors, gynandroblastomas, juvenile granulosa cell tumors, DICER1-associated sarcomas and rare germ cell tumors." (PMID 38136408, 2023). "Unlike ETMR, sarcomas also tend to accumulate mutations in the DRBM, the RNase IIIa, and the Platform domains but do not show any mutational differences in the PACT and TRBP-binding domain and the DICER1 dsRNA-binding fold, which may indicate tissue-specific mutations or mechanisms." (PMID 40361440, 2025).
thyroid (25 papers, 2014 to 2026). "We trace the molecular trajectories from benignity to malignancy in DICER1- and DGCR8-mutated thyroid lesions using multiomic profiling on over 30 DICER1-/DGCR8-mutated samples." (PMID 41657311, 2026). "DICER1 is a key RNase III endoribonuclease involved in microRNA biogenesis and is implicated in both constitutional DICER1-related tumor predisposition and sporadic thyroid tumorigenesis." (PMID 42207300, 2026). "This peculiar tumor expands the spectrum of DICER1-associated thyroid lesions and indirectly establishes a pathogenetic relationship with CMTC." (PMID 40892116, 2025). "The presence of a nodules with high-grade morphological features arising within the tumor (tumor-in-tumor pattern) was identified in five cases, expanding the morphological spectrum of DICER1-associated thyroid lesions." (PMID 40448797, 2025). "Comparison of germline vs somatic DICER1 mutations in thyroid disease: morphology, clinical implications, and testing recommendations." (PMID 41104964, 2025). "We also present clinical and histological triaging criteria for DICER1 sequencing of thyroid lesions, which led to the identification of DICER1 variants in 16 out of 26 cases (62%) when followed." (PMID 38637342, 2024). "Totally, 25 of the 26 DICER1-mutated thyroid lesions exhibited a hotspot mutation, which was shown to be somatic in all 14 for which constitutional DNA was sequenced." (PMID 38637342, 2024). "This study undertakes a comprehensive investigation into DICER1 mutations, focusing on their role in thyroid diseases." (PMID 38254836, 2024). "In summary, as the thyroid manifestations in the context of DICER1 mutations became recognized, the expanded knowledge of thyroid diseases lead us to better understand its pathogenesis and disorders." (PMID 38254836, 2024). "Recent studies evaluating DICER1 mutations and DICER1-driven thyroid disease in both pediatric and adult thyroid nodules revealed thyroid disease as the most common manifestation of DICER1 mutations." (PMID 38254836, 2024). "The effects of DICER1 somatic mutations on miRNA biogenesis and the associated gene expression changes that are relevant for thyroid tumorigenesis are poorly understood." (PMID 36896180, 2023). "Thyroid-specific inactivation of Dicer1 generates mice with severe hypothyroidism and marked loss of differentiation markers (Tg, Nis, Tshr and Tpo), further emphasizing its role in thyroid pathogenesis." (PMID 36896180, 2023). "Ultrasound phenotypes of MNG in the setting of DICER1 mutations were compared with known US features of thyroid malignancy." (PMID 36151231, 2022). "Succeeding DICER1 alterations in the susceptibility of thyroid disease, we reaffirm DGCR8 as another important player of the miRNA microprocessor complex team." (PMID 36499151, 2022). "Beyond DGCR8, somatic DICER1 mutations are reported in follicular-patterned lesions of thyroid (benign and malignant) which underlines the importance of the miRNA processing genes in follicular-patterned lesions." (PMID 36499151, 2022). "Pathogenic variants in DICER1 are associated with increased risks of rare and common neoplasms and thyroid disease in adults and children." (PMID 33630087, 2021). "Furthermore, we identified DICER1 mutations, one of which is previously unreported in thyroid lesions." (PMID 37867524, 2023). "The pooled proportion of thyroid lesions harbouring DICER1 alterations was 5.76% (95% CI, 2.49%-12.78%), with substantial heterogeneity (I2 = 96.94%)." (PMID 42207300, 2026). "Seven studies met criteria for quantitative synthesis, comprising 16,831 thyroid lesions, of which 317 were reported as DICER1-altered." (PMID 42207300, 2026). "Studies were included in the quantitative synthesis only if they provided an interpretable lesion-level numerator and denominator for thyroid lesions harbouring DICER1 alterations." (PMID 42207300, 2026).
thyroid (continued). "This review examines the emerging roles of DICER1 and DGCR8, key components of the miRNA biogenesis pathway, in thyroid pathogenesis, with a particular focus on their association with oncocytic morphology." (PMID 41104964, 2025). "In line with this, downregulating or inactivating mutations of Dicer1, a type III ribonuclease involved in miRNA biogenesis has been described in thyroid and other cancers." (PMID 39409030, 2024). "The link between the malfunction of the miRNA machinery and thyroid disease was first observed in DICER1-syndrome." (PMID 38607000, 2024). "A total of 61 thyroid lesions (54 tumors and 7 cases of thyroid follicular nodular disease; TFND), including 26 DICER1 mutated and 35 DICER1 wildtype controls were subjected to histological re-investigation and clinical follow-up." (PMID 38637342, 2024). "Out of the 61 thyroid lesions (54 tumors and 7 cases of TFND), 26 lesions harbored DICER1 mutations and the remaining 35 were wildtype." (PMID 38637342, 2024). "Our knowledge of thyroid diseases and DICER1 gene alterations has led to newly described entities as well as the reclassification of some thyroid diseases in the WHO’s 5th Endocrine edition." (PMID 38254836, 2024). "In thyroid, DICER1-driven PTCs are infrequent in adult (0-0.4%) but comparatively more prevalent in pediatric PTCs and FTCs (5-10%)." (PMID 36896180, 2023). "While benign thyroids and DICER1-wt DTC show predominance of miR-20a-5p, DICER1-mut DTC have a prominent reduction in 5p:3p strand ratios and express mostly the 3p strand (miR-20a-3p)." (PMID 36896180, 2023). "The fact that DICER1 is a key enzyme in the miRNA maturation and that itself is regulated by miRNAs indicates exceptionally intricate mechanisms in DICER1 dysregulation and thyroid tumorigenesis." (PMID 32163919, 2020). "The presence of distinct histomorphological features in DICER1-associated thyroid lesions, especially in early life and even without a family history, should raise suspicion for DICER1 involvement." (PMID 41104964, 2025). "Consequently, when DICER1 syndrome or DICER1 alterations are known in an individual, closer surveillance for thyroid lesions, as well as those in other organs, is essential." (PMID 41104964, 2025). "Furthermore, a longstanding correlation exists between thyroid disease, the multinodular goiter (MNG), and DICER1 mutations." (PMID 39857323, 2025). "DICER1-related pediatric thyroid disease consists of TFND, follicular adenoma with papillary architecture, DTCs particularly follicular thyroid carcinoma and papillary thyroid carcinoma (macrofollicular type or classical type), PDTC of infancy and childhood, and thyroblastomas." (PMID 38254836, 2024). "In a similar way,the identification of DICER1 and DGCR8 mutationsunderlying DICER1 and FMGS syndromes, respectively, paved the way for extendedanalyses of DICER1 and DGCR8 mutations in somatictissues from patients with thyroid disease." (PMID 39601261, 2024). "The precise role of DICER1 in thyroid oncogenesis is not fully understood." (PMID 35679040, 2022). "Prevalence of germline DICER1 variation; penetrance of malignant tumors and thyroid disease in carriers of germline DICER1 variation; structured, manual review of electronic health records; and DICER1 sequencing of available tumors from an associated cancer registry." (PMID 33630087, 2021). "Clinicians should be aware of a potential germ-line DICER1 mutation when evaluating multinodular goiter in young patients with or without a family history of thyroid diseases." (PMID 24708902, 2014). "Additional thyroid-focused studies that refined the cytomorphologic, histologic, and lesion-spectrum interpretation of DICER1-associated thyroid disease, but lacked a suitable denominator for prevalence meta-analysis, were retained for qualitative clinicopathologic synthesis." (PMID 42207300, 2026).
thyroid (continued). "Similarly, DICER1-mutant thyroid nodules showed greater ultrasound diameter and volume growth than wild-type nodules and transcriptional profiling of mutant tumors showed upregulation of genes implicated in cell proliferation compared to non-neoplastic and hyperplastic thyroid lesions." (PMID 40448797, 2025). "Also, we did not identify somatic DICER1 RNase IIIb hotspot mutations in the thyroid lesions from case 2 and her mother." (PMID 37248399, 2023). "However, if surgery is being performed as definitive treatment, then total thyroidectomy should be advocated, despite the almost universal absence of US features of thyroid malignancy in DICER1-mutated MNGs." (PMID 36151231, 2022). "However, we were not able to establish definitive association of the DICER1 mutation with any specific thyroid disease due to lack of access to detailed clinical histories or affected tissue samples from these patients." (PMID 28222777, 2017). "Moreover, clinicians should be aware of a potential germ-line DICER1 mutation when evaluating multinodular goiter in young patients with or without a family history of thyroid diseases." (PMID 24708902, 2014). "Besides these benign lesions, thyroid entities such as non-invasive follicular thyroid neoplasm with papillary-like nuclear features (NIFTP), invasive encapsulated follicular variants of papillary thyroid cancer (IEFVPTC), PTC, and FTC are also associated with germline and somatic DICER1 mutations." (PMID 41104964, 2025). "The scope of this review extends beyond DICER1 to include DGCR8 and the broader miRNA maturation axis, acknowledging their potential involvement in thyroid tumorigenesis." (PMID 41104964, 2025). "In addition,DICER1 and DGCR8 mutants in thyroid tumorsshare a similar miRNA expression profile, distinguishing them fromDICER1/DGCR8 wild-type tumors." (PMID 39601261, 2024). "This opens new questions about other miRNA biogenesis genes, besides DICER1 and DGCR8, which may have a role in thyroid tumorigenesis." (PMID 38607000, 2024). "So far, partial or total depletion of Dicer1 has never been addressed in a thyroid tumoral context." (PMID 39409030, 2024).
papillary thyroid carcinoma (23 papers, 2015 to 2025). "In the presence of FTA or differentiated thyroid carcinoma with macrofollicular appearance and papillary infoldings with atrophic changes, somatic DICER1 involvement or somatic/constitutional mutation should be suspected, respectively." (PMID 41104964, 2025). "Considering our results, it appears clearly that total loss of Dicer1 in thyroid papillary carcinoma cell lines is deleterious to cell proliferation, migration, and invasion, and by extension to tumor development." (PMID 39409030, 2024). "In the case of malignant diseases, the variants rs7157322 and rs3742330 in the DICER1 gene have been associated with gastric adenocarcinoma and papillary thyroid cancer, respectively." (PMID 39202414, 2024). "All DICER1-mutant differentiated thyroid cancers (DTC) were follicular patterned (six follicular variant PTC and two FTC), none had lymph node metastasis." (PMID 36896180, 2023). "The twin sisters developed some features, such as Sertoli-Leydig cell tumor, multinodular goiter, and papillary thyroid carcinoma, and had positive genetic tests for DICER1 germline mutation." (PMID 37546126, 2023). "Of these, high-quality DNA was available only from the papillary thyroid carcinoma, which harbored multiple somatic DICER1 hotspot variants, in addition to the germline p.Asn1668Ilefs." (PMID 33630087, 2021). "In the thyroid gland, germline DICER1 pathogenic variants are associated with multiple benign thyroid nodules, differentiated thyroid carcinoma, and poorly differentiated thyroid carcinoma (PDTC), while thyroblastoma is an embryonal high-grade neoplasm secondary to somatic mutations." (PMID 40448797, 2025). "Moreover, in papillary thyroid cancer samples, pathogenic somatic variants in the DICER1 gene are associated with a reduction in the abundance of 5p-derived miRNAs." (PMID 39202414, 2024). "Moreover, somatic pathogenic DICER1 variants were found in 10% (3 of 30) of papillary thyroid carcinomas belonging to individuals <18 years of age at time of diagnosis." (PMID 34552563, 2021). "In addition to TFND, differentiated thyroid carcinoma and poorly differentiated thyroid carcinoma have been described in childhood or adolescence related to germline DICER1 mutations, while thyroblastoma is more common in adults and is typically associated with somatic mutations in DICER1." (PMID 40892116, 2025). "Central to this process is Dicer1, a ribonuclease essential for microRNA maturation, whose expression is often reduced in papillary thyroid carcinoma (PTC)." (PMID 41002430, 2025). "Specifically, truncating germline ormissense somatic DICER1 mutations have been reported in smallsubsets of pediatric and adolescent follicular thyroid carcinoma (FTC) andpoorly differentiated thyroid carcinoma (PDTC)." (PMID 39601261, 2024). "Our group was the first to report a higher frequency of DICER1 germline variants in papillary thyroid carcinoma (PTC) cases with oncocytic morphology compared to non-oncocytic counterparts." (PMID 41104964, 2025). "Dicer1 has been found to be altered in papillary thyroid cancer (PTC)." (PMID 39409030, 2024). "Previous study reported that GABPA could inhibit the metastasis of papillary thyroid carcinoma through regulating DICER1." (PMID 36042907, 2022). "Some of the other DICER1-related tumours include cystic nephroma, anaplastic renal sarcoma, Wilms tumour, differentiated thyroid carcinoma, gynandroblastoma, ciliary body medulloepithelioma, embryonal rhabdomyosarcoma and primary brain tumours such as pineoblastoma and pituitary blastoma." (PMID 34552563, 2021). "Therefore, we endorsed that the designation of DICER1-associated well-differentiated thyroid carcinoma/tumor, in accordance with the presence/absence of invasive features respectively, is a more appropriate terminology for these DICER1-associated lesions." (PMID 40448797, 2025).